CTSS (cathepsin S)
Diseases named in the same sentence as CTSS in open-access papers (continued):
Sharing a sentence is not in itself a finding about the gene and the disease.
chronic obstructive pulmonary disease (7 papers, 2018 to 2025). A chronic and progressive lung disorder characterized by the loss of elasticity of the bronchial tree and the air sacs, destruction of the air sacs wall, thickening of the bronchial wall, and mucous accumulation in the bronchial tree. "Elevated levels of the cysteine protease cathepsin S (CatS) are associated with chronic mucoobstructive lung diseases such as cystic fibrosis and chronic obstructive pulmonary disease (COPD)." (PMID 33828414, 2021). "In chronic obstructive pulmonary disease, reduction in CTSS expression prevents loss of lung function, reduces inflammation, and slows the lung tissue remodeling." (PMID 33553270, 2020). "In inflammatory conditions such as cardiovascular disorders and chronic obstructive pulmonary disease, CTSS inhibition has been shown to induce autophagy." (PMID 40794185, 2025). "Inhibition of CTSS activity can decrease incidence of smoking-related chronic obstructive pulmonary disease (COPD)." (PMID 33912521, 2021). "CTSS is located on chromosome 1, 1q21, and its protein is a cysteine protease of papain superfamily and plays an important role in the pathogenesis of chronic obstructive pulmonary disease (COPD)." (PMID 30341237, 2018). "Cathepsin S (CTSS) and Sirtuin-1 (SIRT1) played crucial roles in the pathogenesis of chronic obstructive pulmonary disease (COPD)." (PMID 29976774, 2018).
gastric cancer (7 papers, 2017 to 2024). A primary or metastatic malignant neoplasm involving the stomach. "We observed higher protein expression and positive regulation of cathepsin S in the gastric cancer cell secretome." (PMID 35617240, 2022). "A final and significant outcome of our study is the identification of a restricted number of genes which are up-regulated (IRF1, CTSS, PSMB10, CYP26B1, DHRS3 and TINAGL1) and down-regulated (AHNAK2) by ATRA in all the retinoid-sensitive gastric-cancer cell-lines considered." (PMID 37951921, 2023).
Hypertension (7 papers, 2016 to 2025). The presence of chronic increased pressure in the systemic arterial system. "Cathepsins, particularly CTSB and CTSS, have been implicated in the pathogenesis of hypertension by promoting vascular smooth muscle proliferation, extracellular matrix degradation, cardiomyocyte hypertrophy, and the activation of the RAAS." (PMID 40710492, 2025). "Based on what findings in the present study, we believe that the activities of elastases, such as cathepsin S, were mainly responsible for the vascular stiffening and hypertension observed in the APL-KO mice." (PMID 34782679, 2021). "The adjustment factors of RCS analysis for circulating cathepsin S were age, smoking, alcohol consumption and the history of hypertension." (PMID 33746900, 2021). "The univariate logistic regression analysis showed that clinical factors including alcohol consumption, history of hypertension, BMI, DBP, PBG, 2 h insulin, 2 h C peptide, serum uric acid, eGFR, TC, TG, LDL-C and cathepsin S were possible risk factors of CVD." (PMID 33746900, 2021).
lupus nephritis (7 papers, 2015 to 2022). Glomerulonephritis in the context of systemic lupus erythematosus. "Inhibition of cathepsin S (Cat S) has been shown to improve SLE and lupus nephritis." (PMID 36293172, 2022). "The orally available cathepsin S inhibitor RO546111 was shown to reduce the activation of splenic DCs and the subsequent activation of CD4+ T cells, to diminish hypergammaglobulinemia and anti-dsDNA antibody levels and prevent lupus nephritis progression in MRL/lpr lupus mice." (PMID 26042127, 2015).
Stroke (7 papers, 2017 to 2025). Sudden impairment of blood flow to a part of the brain due to occlusion or rupture of an artery to the brain. "In stroke patients cathepsin S has been shown to exacerbate neuroinflammation, microglial activation, and neuronal injury, with research pointing to potential benefits associated with decreasing its activity following cerebrovascular incident." (PMID 40869205, 2025). "Additionally, cathepsin S (CTSS), a lysosomal protease predominantly expressed by microglia and upregulated after stroke, contributes to BBB leakage and neuroinflammation." (PMID 40244116, 2025). "Beside, restricted tissue expression in macrophages and a broad pH profile of Cathepsin S indicate it could be an ideal target for disease.After stroke onset, Ctss is secreted from microglia onto the extracellular space and subsequently breaks down the blood brain barrier." (PMID 34094642, 2021).
abdominal aortic aneurysm (6 papers, 2012 to 2024). Enlargement and ballooning of the vessel that supplies arterial blood to the abdomen, pelvis and legs. "In addition to its activity within lysosomes of VSMCs and inflammatory cells, CtsS has been linked to lysis of ECM in abdominal aortic aneurysm, intimal hyperplasia, and pulmonary artery hypertension." (PMID 38903966, 2024). "Human abdominal aortic aneurysm (AAA) lesions contain high levels of cathepsin S (CatS), but are deficient in its inhibitor, cystatin C. Whether plasma CatS and cystatin C levels are also altered in AAA patients remains unknown." (PMID 22844527, 2012). "In addition, circulating cathepsin S levels were found to be elevated in the cerebral infarction individuals and the abdominal aortic aneurysm subjects, which represent cerebral and peripheral vascular disease respectively, further supporting our discoveries." (PMID 33746900, 2021). "CTSS participated in the abdominal aortic aneurysm (AAA) formation, and inhibition of CTSS suppressed AAA formation in mice." (PMID 33553270, 2020).
autoimmune disorders (6 papers, 2015 to 2025). "These pathways link CTSS to diverse clinical conditions spanning chronic inflammation, autoimmunity, and immunodeficiencies." (PMID 40692794, 2025). "RO5459072 is a covalent, reversible and selective inhibitor of cathepsin S developed for the treatment of autoimmune conditions, including SS." (PMID 36864622, 2023). "There is evidence that elevated cathepsin S activity may lead to increased MHC-II expression and autoimmunity, implying that inhibition of cathepsin S may be a potential approach in attenuating auto-antigenic T cell responses." (PMID 36864622, 2023). "Although mice deficient in cathepsins B or S generally have functional immune systems, several studies have suggested non-redundant roles for cathepsin S in the context of particular models of autoimmunity." (PMID 26075905, 2015). "The data presented here confirm the non-redundant role of cathepsin S for MHCII maturation in mDC and B cells, both professional APC types known to play major roles in autoimmunity." (PMID 28769925, 2017).
cervical cancer (6 papers, 2017 to 2024). A primary or metastatic malignant neoplasm involving the cervix. "It highlighted the potential of the α-ketoamide-based highly selective cathepsin S inhibitor RJW-58 in the suppression of cervical cancer cell migration and invasion of cervical cancer cells." (PMID 35008759, 2021). "Our previous study demonstrated that hispolon suppresses metastasis through the autophagic degradation of cathepsin S with the activation of ERK in cervical cancer cells." (PMID 29707130, 2018). "Our results indicate that autophagy is essential for decreasing CTSS activity to inhibit tumor metastasis by hispolon treatment in cervical cancer; this finding provides a new perspective on molecular regulation." (PMID 28981104, 2017). "Z-FL-COCHO inhibited CTSS expression in both cervical cancer cell lines and reduced the migration of cervical cancer cells." (PMID 28981104, 2017). "The CTSS inhibitor Z-FL-COCHO was used to investigate the role of CTSS in cervical cancer metastasis." (PMID 28981104, 2017). "This study focused on the major and most abundant CTSs expressed in human neuroblastoma-derived SH-SY5Y and cervical cancer-derived HeLa cells." (PMID 38775843, 2024). "Moreover, SCs displayed increased protein expression of FGF17, CTSS and MMP‐12 after co‐cultivation with cervical cancer cells." (PMID 37830980, 2023). "In turn, SCs activation leads to PNI of cervical cancer by secreting FGF17, CTSS and MMP‐12." (PMID 37830980, 2023).
colon carcinoma (6 papers, 2011 to 2023). "In summary, we demonstrate expression of cathepsin S on the surface of pancreatic and colon carcinoma cells and reveal how cell surface associated cathepsin S can be targeted to mediate ADCC by a fully humanized anti-cathepsin S antibody, Fsn0503h." (PMID 22168338, 2011). "Here we demonstrate expression of cathepsin S on the surface of pancreatic and colon carcinoma cells." (PMID 22168338, 2011). "Interestingly, we also detected an increased Cathepsin S release, which is an important finding as this lysosomal enzyme has been reported to contribute to angiogenesis and carcinogenesis, particularly in the case of colon cancer." (PMID 35336037, 2022).
diabetic nephropathy (6 papers, 2018 to 2025). "More importantly, treatment of diabetic kidney disease in uninephrectomized db/db mice with a selective CTSS inhibitor (RO5461111) improved endothelial injury, albuminuria, and glomerulosclerosis as well as albumin leakage in the retina." (PMID 36059966, 2022). "According to a recent study, macrophage-derived CTSS may hasten endothelial damage and nephrosclerosis in diabetic nephropathy." (PMID 36814902, 2023).
Insulin resistance (6 papers, 2011 to 2023). Increased resistance towards insulin, that is, diminished effectiveness of insulin in reducing blood glucose levels. "Examples of other pro-inflammatory proteins affiliated with inflammation but not liver insulin resistance were cathepsin S or granzyme A." (PMID 21978410, 2011).
liver cancer (6 papers, 2015 to 2024). An epithelial or non-epithelial malignant neoplasm that arises from the liver. "CD47 positive liver cancer cells preferentially secreted cathepsin S (CTSS), which regulated liver tumor-initiating cells through the CTSS/protease-activated receptor 2 (PAR2) loop." (PMID 25907256, 2015).
renal carcinoma (6 papers, 2016 to 2020). A carcinoma arising from the epithelium of the renal parenchyma or the renal pelvis. "In the current study, we investigated the effect of cathepsin S inhibition on ER stress as well as the molecular mechanisms underlying cathepsin S inhibition-induced ER stress in human renal carcinoma cells." (PMID 30120227, 2018). "In our study, YM155 induced lysosomal membrane permeabilization (LMP), and then released cathepsin S into cytosol from lysosome in human renal carcinoma cells." (PMID 27528031, 2016). "In conclusion, our results suggested that YM155 induces TRAIL-mediated apoptosis through cathepsin S-dependent down-regulation of Mcl-1 expression and down-regulation of c-FLIP expression via down-regulation of NF-κB transcriptional activity in human renal cancer cells." (PMID 27528031, 2016).
triple-negative breast carcinoma (6 papers, 2016 to 2022). An invasive breast carcinoma which is negative for expression of estrogen receptor (ER), progesterone receptor (PR), and human epidermal growth factor receptor 2 (HER2). "Inhibition using a CTSS inhibitor VBY-999, reduced CTSS mediated metastases in an MDA-MB-231 triple negative breast cancer model." (PMID 27097645, 2016). "Similarly, it had been reported that CTSS was over-expressed in triple-negative breast cancer, and the inhibition of CTSS could be conducted by inhibiting the growth and metastasis of triple-negative breast cancer." (PMID 34266404, 2021).
breast tumors (5 papers, 2015 to 2023). "Breast tumor cells equipped with cathepsin S are capable of migrating across this strict and highly selective barrier by enabling the cleavage of these restricting junction proteins." (PMID 36002710, 2023). "However, due to the selectivity of BMV157 for cathepsin S, its fluorescence signal in breast tumors was weaker than that of BMV109." (PMID 36002710, 2023).
dry eye (5 papers, 2017 to 2024). "Here we show that oral delivery of the cathepsin S inhibitor RO5461111 through specially formulated chow effectively reduces the impact of age-associated dry eye on the ocular surface of mice." (PMID 37540176, 2023). "Altogether, our results demonstrate the feasibility of oral administration of a cathepsin S inhibitor and its potential usefulness in ameliorating age-associated dry eye while shedding light on the underlying therapeutic mechanisms." (PMID 37540176, 2023). "Thus, dietary blockade of cathepsin S represents a potential therapeutic intervention in age-associated dry eye." (PMID 37540176, 2023). "Additionally, research indicated that degradation of PRG4 by CTSS might be linked with diminished ocular surface lubrication in SS, explaining the dry eye symptom." (PMID 37727764, 2023). "Aged C57BL/6J (B6) mice have increased levels of cathepsin S, and aged cathepsin S (Ctss−/−) knockout mice are resistant to age-related dry eye." (PMID 37540176, 2023). "In this regard, herein we show that 12-week and 28-week-long treatments with a cathepsin S inhibitor improved age-related dry eye parameters, a strength of our findings." (PMID 37540176, 2023). "In this study, we subjected mice aged 15.5 to 17 months to a cathepsin S inhibition diet to investigate if cathepsin S blockade could be used to revert the age-related dry eye phenotype in mice." (PMID 37540176, 2023).
endothelial dysfunction (5 papers, 2017 to 2024). In vascular diseases, endothelial dysfunction is a systemic pathological state of the endothelium (the inner lining of blood vessels) and can be broadly defined as an imbalance between vasodilating and vasoconstricting substances produced by (or acting on) the endothelium. "It has also been found that, in mice, serum CTSS level and markers of inflammation-related endothelial dysfunction, such as soluble tumor necrosis factor receptor (sTNFR1, sTNFR12), increase with the decrease of eGFR." (PMID 34819020, 2021). "We hypothesized that progressive CKD drives the release of cathepsin-S (Cat-S), a cysteine protease that promotes endothelial dysfunction and cardiovascular complications." (PMID 28240259, 2017).
follicular lymphoma (5 papers, 2021 to 2026). Follicular lymphoma is a form of non-Hodgkin lymphoma characterized by a proliferation of B cells whose nodular structure of follicular architecture is preserved. "Increased CTSS expression has been linked to tumor progression in follicular lymphoma due to decreased CD8+ T cell recruitment." (PMID 37173324, 2023). "Cathepsin S is upregulated in follicular lymphoma, and an activating mutation Y132D drives lymphomagenesis through alterations in antigen presentation and a pro-tumorigenic microenvironment." (PMID 38026637, 2023). "Prof. Dheilly found that follicular lymphoma patients harbor a recurrent hotspot mutation targeting tyrosine 132 (Y132D) in cathepsin S (CTSS) that enhances protein activity." (PMID 34266404, 2021). "Dysregulation of CTSS activity was also recently reported for hematological malignancies: CTSS mutations, such as the recurrent Y132D hotspot in follicular lymphoma, enhance enzymatic activity and modulate antigen processing, influencing both CD4+ and CD8+ T cell-mediated responses." (PMID 41597203, 2026). "CTSS is a cysteine protease critical for MHC Class II loading and is frequently mutated in follicular lymphoma." (PMID 37173324, 2023). "CTSS mutations (but not editing) have even explicitly been shown to be tumor promoting in follicular lymphoma." (PMID 39062643, 2024).
lymphoma (5 papers, 2021 to 2024). A malignant (clonal) proliferation of B- lymphocytes or T- lymphocytes which involves the lymph nodes, bone marrow and/or extranodal sites. "Conversely, loss of CTSS activity in aggressive mouse lymphoma xenograft restrain lymphoma growth by recruiting and enhancing CD8+ T cells cytotoxic activity while impairing communication with CD4+ TFH cells." (PMID 34335584, 2021). "Loss of CTSS activity reduces lymphoma growth by limiting communication with CD4 T follicular helper cells while inducing antigen diversification and activation of CD8 T cells." (PMID 34923982, 2021). "Increased cell proliferation and reduced apoptosis in lymphoma, which could be associated with elevated levels of CTSS, have led to higher cholesterol consumption and, consequently, reduced circulating HDL-C levels." (PMID 39712508, 2024). "Also, in order to better understand the role of CTSS in the origin and development of lymphoma, its association with cystatin C (Cys C), lipids, and inflammatory markers was analysed." (PMID 39712508, 2024). "The purpose of this study is to analyse CTSS as a potential biomarker in lymphoma." (PMID 39712508, 2024). "Additionally, the objective was to evaluate the CTSS as a potential biomarker in lymphoma." (PMID 39712508, 2024).
Sepsis (5 papers, 2015 to 2025). Sepsis is defined as life-threatening organ dysfunction caused by a dysregulated host response to infection. "In this study, we demonstrated that monocyte marker gene CTSS is a protective factor for sepsis risk and prognosis." (PMID 40115073, 2025). "An incremental decrease in the expression level of CTSS was observed with declining endotype class, indicating a potential association between the expression level and the progression of sepsis." (PMID 40115073, 2025). "In the context of sepsis, CTSS has been implicated in modulating immune responses and inflammation." (PMID 40861493, 2025). "Monocyte marker CTSS represent a promising target for the diagnosis and prognosis evaluation of sepsis and plays a critical role in monocytes activation, tissue inflammatory response and macrophages infiltration." (PMID 40115073, 2025). "Subsequently, to further elucidate the possible role of CTSS in monocytes/macrophages during sepsis, we assessed the infiltration of macrophages into the septic and normal lungs of mice." (PMID 40115073, 2025). "This is consistent with our findings that CTSS is one of the key DEGs in sepsis; however, this is the first time it has been found to play a role in the necroptotic process of sepsis." (PMID 40861493, 2025). "Following the administration of LPS, we investigated the role of CTSS in monocyte activation during sepsis by treating monocytes obtained from healthy individuals with a CTSS agonist." (PMID 40115073, 2025). "The increased expression of CTSS might contribute to the excessive inflammation and tissue damage in sepsis." (PMID 40861493, 2025). "Thus, CTSS agonist probably serves as new drug for clinical protection against sepsis." (PMID 40115073, 2025). "Similarly, in this study, we also demonstrated that sepsis induced the downregulation of CTSS in monocytes and CTSS agonist administration effectively inhibited the activation of peripheral monocytes, improved the tissue inflammatory response and macrophages infiltration." (PMID 40115073, 2025). "Thus, we questioned whether sepsis-induced CTSS downregulation is involved in activating monocytes." (PMID 40115073, 2025).
systemic sclerosis (5 papers, 2022 to 2025). A chronic disorder, possibly autoimmune, marked by excessive production of collagen which results in hardening and thickening of body tissues. "The majority of studies report elevated cathepsin S levels in association with the specific disease process, however, a recent study has reported decreased cathepsin S levels in patients with systemic sclerosis associated interstitial lung disease." (PMID 35620518, 2022). "In systemic sclerosis (SSc), the expression of ADAR1 p150 and cathepsin S (CTSS) is elevated in both skin and peripheral blood, accompanied by significantly increased editing of an Alu element in the 3’-UTR of the CTSS gene." (PMID 41446042, 2025).